CENPH (centromere protein H)
Description:
Component of the CENPA-NAC (nucleosome-associated) complex, a complex that plays a central role in assembly of kinetochore proteins, mitotic progression and chromosome segregation. The CENPA-NAC complex recruits the CENPA-CAD (nucleosome distal) complex and may be involved in incorporation of newly synthesized CENPA into centromeres. Required for chromosome congression and efficiently align the chromosomes on a metaphase plate.
Tractability: PROTAC: UniProt records ubiquitination sites on it; ubiquitination databases record sites on it.
Gene: Protein-coding gene on chromosome 5 (69,189,542 to 69,210,357, forward strand). Ensembl gene ENSG00000153044.
Subcellular location: Nucleus; Chromosome, centromere, kinetochore
Subcellular location (Human Protein Atlas): Nucleoli rim; Nucleoplasm; Mitotic chromosome
Pathways (Reactome):
Cell Cycle: Amplification of signal from unattached kinetochores via a MAD2 inhibitory signal; Deposition of new CENPA-containing nucleosomes at the centromere; EML4 and NUDC in mitotic spindle formation; Mitotic Prometaphase; Resolution of Sister Chromatid Cohesion; Separation of Sister Chromatids
Signal Transduction: RHO GTPases Activate Formins
Gene Ontology:
Molecular function: kinetochore binding; protein binding
Biological process: chromosome segregation; kinetochore organization; mitotic spindle organization; kinetochore assembly
Cellular component: chromosome; inner kinetochore; kinetochore; nucleoplasm; nucleus; cytosol
Genetic constraint (gnomAD): Loss-of-function variants: 4 observed, 2.27 expected, observed/expected ratio (o/e) 1.76, 90% interval 0.7 to 1.94. That is too few expected variants to judge how well the gene tolerates losing a copy. Missense variants: 72 observed, 43.83 expected, observed/expected ratio (o/e) 1.64, 90% interval 1.35 to 1.92. Synonymous variants: 29 observed, 19.72 expected, observed/expected ratio (o/e) 1.47, 90% interval 1.09 to 1.89.
Homologues: Orthologues: chimpanzee CENPH (99% identical), macaque CENPH (95% identical), pig CENPH (79% identical), dog CENPH (77% identical), guinea pig CENPH (68% identical), rabbit CENPH (68% identical), mouse Cenph (64% identical), rat Cenph (64% identical), tropical clawed frog cenph (39% identical), zebrafish cenph (23% identical).
Diseases named in the same sentence as CENPH in open-access papers:
CENPH is named in the same sentence as 30 diseases in open-access papers, as found by Europe PMC text mining. Sharing a sentence is not in itself a finding about the gene and the disease. The quoted sentences say what the papers report.
nasopharyngeal carcinoma (9 papers, 2008 to 2025). A carcinoma arising from the nasopharyngeal epithelium. "We previously reported that Sp1 activates the transcription of Bmi1 and CENPH in nasopharyngeal carcinoma." (PMID 25099028, 2014). "Centromere protein H (CENPH) is considered to be an essential part of the active centromere complex, and its overexpression is highly related to poor prognosis in renal cell carcinoma, nasopharyngeal carcinoma, CRC, and HCC." (PMID 33564675, 2021).
colorectal cancer (7 papers, 2008 to 2023). A primary or metastatic malignant neoplasm that affects the colon or rectum. "As one of the essential components of active kinetochore, overexpression of centromere protein H (CENPH) in human colorectal cancer was shown to be a major cause of chromosomal instability (CIN)." (PMID 37328854, 2023). "Many studies have shown that CENPH is closely associated with human cancers, including colorectal cancer, renal cell carcinoma, non-small cell lung cancer as well as breast cancer (Walian, Hang & Mao, 2016)." (PMID 33005492, 2020). "Our data suggest that LGR5, KCNN4, TNS4 and CENPH are correlated with radiation sensitivity of colorectal cancer cells, and the indicator composed by them can reflect the prognosis of colorectal cancer patients undergoing radiation therapy." (PMID 37328854, 2023). "In conclusion, through the sorting and analysis of the radiation resistance projects in the GEO database and tumor vs. normal tissue project in TCGA-COREAD database, we established a gene panel (LGR5, KCNN4, TNS4 and CENPH) in colorectal cancer patients receiving radiotherapy." (PMID 37328854, 2023). "Prognostic indicator based on TCGA colorectal cancer patients containing four key radiation resistance genes (LGR5, KCNN4, TNS4, CENPH) was established." (PMID 37328854, 2023).
tongue cancer (6 papers, 2009 to 2025). A malignant neoplasm affecting the tongue. "And CENPH has been considered to be associated with tumor progression and poor prognosis in NSCLC, tongue cancer, esophageal cancer and gastric cancer." (PMID 37328854, 2023). "The expression of centromere protein H (CENPH) was upregulated in cervical cancer 、breast cancer 、and gastric cancer, promoting the proliferation of gastric cancer cells and tongue cancer cells, and it could be used as an independent prognostic biomarker for cervical cancer and breast cancer." (PMID 37697245, 2023).
cervical carcinoma (4 papers, 2012 to 2025). A carcinoma arising from either the exocervical squamous epithelium or the endocervical glandular epithelium. "Previous studies have shown that high expression of CENPH leads to poor prognosis in patients with cervical carcinoma." (PMID 36341103, 2022).
gastric cancer (4 papers, 2021 to 2024). A primary or metastatic malignant neoplasm involving the stomach. "Similarly, studies in gastric cancer have highlighted the prognostic utility of combining Ki-67 with centromere protein H (CENP-H)." (PMID 39685591, 2024). "Cell cycle marker CENPH pay key role in proliferation of gastric cancer cells, but this gene might be involved in proliferation of pituitary prolactinoma." (PMID 33709028, 2021).
esophageal cancer (3 papers, 2008 to 2023). A primary or metastatic malignant neoplasm involving the esophagus. "Interestingly, CENPH is overexpressed and is prognostic in esophageal carcinoma." (PMID 35496042, 2022). "The aim of the present study was to clarify the expression of Centromere protein H (CENP-H), one of the fundamental components of the human active kinetochore, in esophageal carcinoma and its correlation with clinicopathological features." (PMID 18700042, 2008).
hepatic carcinoma (2 papers, 2021 to 2023). "Meanwhile, knockdown of CENPH retarded the growth of Hep3B, hepatic carcinoma cell, subcutaneous xenograft, and decreased the expression of Ki-67 and BCL-2." (PMID 37328854, 2023). "Furthermore, centromere protein H (CENP-H) has been demonstrated to be a novel biomarker related to the survival in patients with hepatocellular carcinoma." (PMID 33833984, 2021).
lung carcinoma (2 papers, 2021 to 2022). "Further analysis showed that high expression levels of CENPH protein were positively correlated with Ki-67 and associated with a poor prognosis, particularly in patients diagnosed with stage I–II lung cancer." (PMID 34631307, 2021). "Chinese researchers were the first to report the relationship between CENPH and NSCLC and showed that both mRNA levels and protein levels were over-expressed in cases of lung cancer." (PMID 34631307, 2021).
lung adenocarcinoma (1 paper, 2021). A carcinoma that arises from the lung and is characterized by the presence of malignant glandular epithelial cells. "Our analysis also showed that CENPH was overexpressed in cases of lung adenocarcinoma and correlated with a poor prognosis." (PMID 34631307, 2021). "Only the expression levels of the CENPH gene were found to be significantly different when compared between lung adenocarcinoma and normal tissue." (PMID 34631307, 2021).
prostate carcinoma (1 paper, 2018). A carcinoma that arises from epithelial cells of the prostate gland. "Selected ARA-lincRNAs are neighbors of protein-coding genes WDR5, ZNF706, TFRC, and FLNA, which have been described as up-regulated in prostate cancer, and of CENPH and RAB11FIP3, which have been shown to play a role in many other types of cancer." (PMID 29875794, 2018).
renal carcinoma (1 paper, 2021). A carcinoma arising from the epithelium of the renal parenchyma or the renal pelvis. "The expression of CENPH is known to be elevated and associated with the progression of many cancers, such as oral, tongue, nasopharyngeal, hypopharyngeal, lung, breast, esophageal, gastric, colorectal, hepatocellular, and renal cancer." (PMID 34631307, 2021).
triple-negative breast carcinoma (1 paper, 2020). An invasive breast carcinoma which is negative for expression of estrogen receptor (ER), progesterone receptor (PR), and human epidermal growth factor receptor 2 (HER2). "Finally, we validated the expression levels of NUF2, FAM83D and CENPH in 14 pairs of triple negative breast cancer paired tissues by using RT-qPCR." (PMID 33005492, 2020). "However, there is no current evidence on the correlation between CENPH and triple negative breast cancer." (PMID 33005492, 2020).
cancer (14 papers, 2008 to 2025). A tumor composed of atypical neoplastic, often pleomorphic cells that invade other tissues. "The modules significantly contained the nodes (i.e., CENPA, CENPN, and CENPH) which are associated with different cancers and disease progression." (PMID 30658502, 2019). "b); and the CNVs (deletion) and expression of MCM6 and CENPH, which enhanced cancer cell proliferation, stemness, and metastasis and promoted cancer development, were also increased with the increase of Gleason grade." (PMID 33985534, 2021). "Therefore, the cancer-promoting role of Sp1 may also be mediated by transcriptional activation of its downstream genes, such as Bmi1 and CENPH." (PMID 25099028, 2014). "On the other hand, “hub genes” of four other modules contain POU2F3 (↑), CENPH (↑), PCSK6 (↑) and HERC2 (↑), BCAR3 (↑), DOHH (↑), NLK (↑), SCN2A (↑), CACNA2D3 (↓) and CTNND2 (↓), which were commonly reported related to cancer." (PMID 27602771, 2016).
tumor (11 papers, 2008 to 2024). "Four genes (CENPH, MYLIP, PITX3, and TRAF3IP3) were eventually identified; these were associated with tumor-infiltrating immune cells, the proliferation of tumor cells, and cell adhesion." (PMID 34631307, 2021). "And the effect of CENPH may be highly related to Survivin, an inhibitor of apoptosis protein family, which helps tumor cells to survive and restore proliferation under harmful stress." (PMID 37328854, 2023). "Furthermore, the expression levels of CENPH gradually increased in stages I–IV, suggesting that the expression of this gene is closely related to tumor progression." (PMID 34631307, 2021).
CENPH also shares sentences with these, for which no sentence is quoted: breast cancer (5 papers); lymph node metastasis (3); renal cell carcinoma (3); colon cancer (2); liver cancer (2); calcinosis (1); colorectal gastrointestinal stromal tumor (1); esophageal adenocarcinoma (1); esophageal squamous cell carcinoma (1); hypopharyngeal squamous cell carcinoma (1); non-small cell lung carcinoma (1); oral cancer (1); oral squamous cell carcinomas (1); Sjögren's syndrome (1); squamous cell carcinoma of the tongue (1); Telangiectasia (1).